ACTR1B (actin related protein 1B)
Description:
Component of a multi-subunit complex involved in microtubule based vesicle motility. It is associated with the centrosome.
Synonyms: ARP1B; CTRN2; PC3
Tractability: Antibody: its Gene Ontology location is reachable by antibodies, with high confidence. PROTAC: ubiquitination databases record sites on it; its protein half-life has been measured.
Gene: Protein-coding gene on chromosome 2 (97,655,939 to 97,664,114, reverse strand). Ensembl gene ENSG00000115073.
Subcellular location: Cytoplasm, cytoskeleton; Cytoplasm, cytoskeleton, microtubule organizing center, centrosome
Subcellular location (Human Protein Atlas): Microtubules; Cytokinetic bridge; Cytosol; Primary cilium
Pathways (Reactome):
Immune System: MHC class II antigen presentation; Neutrophil degranulation
Gene Ontology:
Molecular function: protein binding; structural constituent of cytoskeleton
Biological process: cytoskeleton organization
Cellular component: centrosome; cytoplasm; extracellular exosome; membrane; cytosol; dynactin complex; extracellular region; ficolin-1-rich granule lumen; secretory granule lumen; cytoskeleton; microtubule organizing center
Genetic constraint (gnomAD): Loss-of-function variants: 35 observed, 47.96 expected, observed/expected ratio (o/e) 0.73, 90% interval 0.56 to 0.97. The upper end of that interval is the gene's LOEUF score, 0.97, which puts it in group 4 of 6, group 1 being the genes least tolerant of losing a copy. Missense variants: 471 observed, 512.54 expected, observed/expected ratio (o/e) 0.92, 90% interval 0.85 to 0.99. Synonymous variants: 207 observed, 207.66 expected, observed/expected ratio (o/e) 1, 90% interval 0.89 to 1.12.
Homologues: Orthologues: chimpanzee ACTR1B (100% identical), mouse Actr1b (99% identical), rat Actr1b (99% identical), dog ACTR1B (99% identical), rabbit ACTR1B (99% identical), guinea pig ACTR1B (98% identical), pig ACTR1B (98% identical), chimpanzee ACTR1B (95% identical), macaque ACTR1B (91% identical). Paralogues in human: ACTR1A (90% identical), ACTG1 (56% identical), ACTB (55% identical), ACTA2 (55% identical), ACTC1 (54% identical), ACTG2 (54% identical), ACTA1 (54% identical), ACTBL2 (53% identical), ACTR2 (44% identical), ACTRT3 (41% identical), ACTRT2 (41% identical), ACTRT1 (40% identical), and 14 more.
Diseases named in the same sentence as ACTR1B in open-access papers:
ACTR1B is named in the same sentence as 5 diseases in open-access papers, as found by Europe PMC text mining. Sharing a sentence is not in itself a finding about the gene and the disease. The quoted sentences say what the papers report.
schizophrenia (2 papers, 2014 to 2024). A major psychotic disorder characterized by abnormalities in the perception or expression of reality. "We also observed an association between CT1 and rs11692435 (p = 1.17 × 10−12), a schizophrenia-related locus, within the ACTR1B gene." (PMID 39448598, 2024).
breast carcinoma (1 paper, 2022). "The following genes were reported to be higher expressed in breast cancer samples of cases compared to controls in two different studies but were reported to be lower expressed in another study: SFRP1, ACTR1B, FASTK, TMEM219, NDUFA3, ATP5I." (PMID 36627894, 2022).
ACTR1B also shares sentences with these, for which no sentence is quoted: carcinoma (1 paper); COVID-19 (1); tumor (1).